ALB (albumin)
Diseases named in the same sentence as ALB in open-access papers (continued):
Sharing a sentence is not in itself a finding about the gene and the disease.
glioma (66 papers, 2008 to 2026). A benign or malignant brain and spinal cord tumor that arises from glial cells (astrocytes, oligodendrocytes, ependymal cells). "Although albumin is generally restricted from entering the brain, the rapid growth of highly metabolically active tumors causes them to become starved for nutrients, and tumor cells significantly enhance albumin uptake into glioma tissues for use as an amino acid and energy source." (PMID 36945032, 2023). "It is known that the level of serum albumin, which makes up 52.9–66.9% of the total protein, positively correlates with the survival of patients with glioma." (PMID 40426873, 2025). "For example, albumin-consolidated AIEgens were constructed for boosting glioma and cerebrovascular NIR-II fluorescence imaging, and these albumin-based AIE nanoprobes enable the limited fluorescence imaging-guided surgery of brain tumor and cerebral ischemia." (PMID 38323081, 2024). "In particular, ZnPcS with an amphiphilic structure was used to target gliomas overexpressing SPARC by strongly binding to albumin in situ." (PMID 36945032, 2023). "Because tumor cells, including gliomas, proliferate abnormally fast, they consume a significant amount of energy to maintain this growth process and require many nutrients, such as albumin." (PMID 36945032, 2023). "SPARC has been found to be over-expressed in glioma and provides a mechanism for albumin-based drug delivery to the CNS." (PMID 37213306, 2023). "We previously reported that maleimide-functionalized closo-dodecaborate albumin conjugate (MID-AC) with albumin as the drug delivery system is an effective boron carrier for the F98 glioma-bearing rat brain tumor model." (PMID 36979069, 2023). "Previously, we reported that maleimide-functionalized closo-dodecaborate albumin conjugate (MID-AC) is effective as a boron-10 carrier for BNCT in an F98 glioma-bearing rat brain tumor model." (PMID 36979069, 2023). "Albumin functions as a ligand that can precisely target gliomas and trigger transcytosis across the BBB, enabling efficient targeting and intertumoral drug entry for brain tumor treatment." (PMID 36945032, 2023). "In order to evaluate the targeting impact of nanoparticles on glioma, several albumin nanoparticles loaded with BODIPY were injected intravenously into mice that had developed U87-Luci cancer cell-induced tumors." (PMID 37836018, 2023). "We found that the albumin concentration in the cystic fluid was maximal in glioma samples, but albumin was also one of the most abundant proteins in the cystic fluids collected from SM and CS." (PMID 37627098, 2023). "The key to this phenomenon is that SPARC is overexpressed in solid cancers, including glioma; thus, it not only triggers tumor growth and angiogenesis, but also increases the absorption of albumin, helping glioma proliferation." (PMID 36945032, 2023). "The efficacy of boron neutron capture therapy (BNCT) targeting integrin αvβ3 in glioma cells in the brain of rats using a cRGD-functionalized MID-albumin conjugate (cRGD-MID-AC) was evaluated." (PMID 36979069, 2023). "Albumin nanoparticles modified with para-mentha-8-thiol-3-one successfully delivered drugs to glioma tumors in the brain by overcoming the BBB." (PMID 37836018, 2023). "In particular, absorption of nutrients, such as albumin, is required to support the rapid proliferation of gliomas." (PMID 36945032, 2023). "Secreted protein acidic and rich in cysteine (SPARC) is an extracellular glycoprotein expressed in gliomas and binds to albumin, suggesting that it plays an important role in tumor uptake of the ICG-HSA complex." (PMID 36614294, 2023). "We observed that in glioma patients, preoperative WBCs, neutrophil and monocyte counts were significantly higher than in other groups, while lymphocyte counts and albumin levels were significantly lower." (PMID 36483052, 2022).
glioma (continued). "IRDye800-H-ferritin nanocarrier (IRDye800-HFn) was applied in imaging hypoxia in glioma, and albumin-based gold (Au) NP, ICG/AuNR@BCNP, was used as theranostics for glioma- and hypoxia-alleviating treatment." (PMID 34650961, 2021). "Of equal interest was to determine the efficacy of those glioma cell lines to regenerate the antiproliferative potencies of albumin–MTX analogues which lost their native three-dimensional configurations." (PMID 35056966, 2021). "Previous studies have shown albumin-based nanocarriers to engage cell-surface receptors overexpressed in glioma cells and tumor vessel endothelium, SPARC, and gp6034,35." (PMID 33173024, 2020). "based on the combination of plasma FIB and albumin levels can predict progression-free survival and OS in patients with high-grade gliomas." (PMID 33363021, 2020). "The receptors (overexpressed in glioma) for the albumin were identified to be Gp60 (over-expressed in the endothelium that in turn, increase extravascular leakage of Albumin) and SPARC." (PMID 31195727, 2019). "While albumin in healthy individuals cannot overcome the blood–brain barrier, different brain tumors, like gliomas, can enhance its uptake, as they can represent an optimal fuel for increasing amino-acids intake and energy." (PMID 31195727, 2019). "In this study, we evaluate tHct in acute stroke and in glioma models using a new approach to map tHct across the brain, a dual isotope autoradiography, based on injections of 125I-labeled albumin and 99mTc-lalbeled red blood cells in the same animal." (PMID 29959336, 2018). "The survival analysis showed that younger age; IDH-1 mutations; higher albumin, AGR, and PNI levels; and lower NLR, PLR, and fibrinogen levels were favorable prognostic factors of OS in all gliomas and glioblastomas (GBMs)." (PMID 30154718, 2018). "In 2008, the team successfully visualized overexpressed c-MET in C6 (rat glioma) rat models in vivo by MRI based on a targeting contrast agent, anti-c-MET-Gd-DTPA-albumin, an anti-c-MET antibody linked to biotinylated Gd-DTPA-albumin." (PMID 28485003, 2017). "Its linkage to bovine serum albumin (BSA) yielded a conjugate with profound antiproliferative efficacy in a MTX-sensitive glioma cell line." (PMID 27403959, 2016). "An identical parameter for radiolabeled serum albumin measured by quantitative autoradiography also declined after dexamethasone treatment (8 mg/kg, given over 48 h) in a rat model of RG-2 glioma." (PMID 24376814, 2013). "Various authors have found glioma cells to migrate towards serum proteins, such as albumin, and phospholipids, such as lysophosphatic acid." (PMID 21978494, 2011). "To this end, we subjected U-251MG glioma cells for 30 minutes to AdGFP in medium containing various concentrations of human albumin." (PMID 22022354, 2011). "With regard to glioma, several nutritional and inflammatory biomarker scores, such as the Controlling Nutritional Status (CONUT) score, the Prognostic Nutritional Index (PNI), and hematologic biomarkers such as albumin or fibrinogen have been established to predict OS in glioma patients." (PMID 40690185, 2025). "While variables included in PANWARDS (platelet count, albumin, comorbidities) may inform future work, any tool for PwG must go further and incorporate glioma-specific factors such as tumour grade, size, and location." (PMID 41204188, 2025). "Therefore, it is very appealing that cRGD-MID-AC with 12 boron atoms per molecule can reach glioma cells and remain in these cells for a long time owing to the properties of human serum albumin." (PMID 36979069, 2023). "Albumin polymer-based systems can also be used for targeted therapy for in situ gliomas." (PMID 37177365, 2023). "Moreover, there are several potential intraoperative fluorescence imaging alternatives, such as sodium fluorescein, second window indocyanine green, and 5-aminofluorescein-labeled albumin, which were investigated regarding glioma surgery." (PMID 35565263, 2022).
glioma (continued). "Thus, for neutron source efficacy evaluation, ~30 μM of boronated albumin can be used to minimize the effect of the drug on glioma cell colony formation." (PMID 34770947, 2021). "The conjugation of boron compounds and human serum albumin (HSA)—a carrier protein with a long plasma half-life—is expected to extend systemic circulation of the boron compounds and increase their accumulation in human glioma cells." (PMID 34770947, 2021). "Surprisingly, ALB was described as a potential novel protein marker for glioma." (PMID 34873410, 2021). "Interestingly, the albumin covered area was reduced in glioma tissues of Ccr2KO animals accompanied by less albumin-stained tumor vessels indicating increased stability and less permeability of blood vessels dependent on Ccr2-deficiency." (PMID 32668709, 2020). "Functionalization of IONPs and MnO NPs with folate or albumin have enabled specific targeting of glioma cells in orthotopic mouse models of glioma, enabling longer periods of signal enhancement on MRI and could possibly aid in differentiating between true tumor signal versus pseudoprogression." (PMID 35875504, 2022). "Besides, AKT1, JUN, ALB, MAPK1, and TNF display good diagnostic value in glioma." (PMID 34873410, 2021). "cRGD-MID-AC, cyclic RGD-functionalized closo-dodecaborate albumin conjugates with maleimide, has been shown to have a therapeutic effect in BNCT in an experimental F98 glioma-bearing rat brain tumor model." (PMID 36979069, 2023). "Another study reported that borneol or muscone were conjugated with bovine serum albumin (BSA) to prepare aromatic resuscitation drugs modified albumin‐based nanoparticles, which can enhance drugs across the BBB for the treatment of glioma." (PMID 36925685, 2023). "Herein, we demonstrate a precision photodynamic tumor therapy using a photosensitizer (ZnPcS) capable of binding to albumin in situ, which can increase the permeability of the BBB and accurately target glioma." (PMID 36945032, 2023). "Albumin-based delivery systems have also been shown to interact with cell surface receptors such as SPARC and gp60, which are overexpressed on glioma cells and tumor endothelia." (PMID 37836018, 2023). "The albumin nanoparticles modified with dual ligands efficiently passed through the BBB and achieving biomimetic delivery to glioma and GAMs, inhibited the glioma cell proliferation and reprogrammed M2-GAMs to M1 phenotype." (PMID 36275720, 2022). "Among laboratory parameters, patients with glioma WHO IV had significantly higher WBCs, neutrophils, and monocyte counts (p value < 0.05), and significantly lower lymphocyte counts and albumin levels compared to healthy controls (p value < 0.05)." (PMID 36483052, 2022). "The developed CAT-integrated albumin theranostic nanoprobe (ICG/AuNR@BCNP) penetrated the blood–brain barrier and accumulated into glioma via albumin-binding protein-mediated transportation to perform theranostic functions." (PMID 35624636, 2022). "For example, albumin NPs conjugated with low molecular weight protamine is designed to bind to albumin-binding protein (e.g., SPARC and gp60) on glioma and tumor vessel endothelium." (PMID 34576281, 2021). "By target harvesting, six core genes including AKT1, JUN, ALB, MAPK3, MAPK1, and TNF were screened from a total of 205 targets of luteolin against the glioma network." (PMID 34873410, 2021). "On univariate analysis, increased neutrophil-to-lymphocyte ratio (NLR), platelet-to-lymphocyte ratio (PLR), and monocyte-to-lymphocyte ratio (MLR), and decreased albumin-to-globulin ratio (AGR), all predicted poor prognosis in Grade II/III gliomas." (PMID 31444316, 2019). "The levels of albumin, AGR, and PNI significantly decreased in GBMs, in contrast to Grade III and II gliomas." (PMID 30154718, 2018). "We found that nutrition-related markers, such as albumin, AGR, and PNI, were significantly negatively correlated with age in all gliomas (p < 0.001) and GBMs (p < 0.001)." (PMID 30154718, 2018).
glioma (continued). "In gliomas, neutrophil-to-lymphocyte ratio (NLR), platelet-to-lymphocyte ratio (PLR), fibrinogen, albumin-to-globulin ratio (AGR), and prognostic nutrition index (PNI) have been identified as prognostic markers." (PMID 30154718, 2018). "All the albumin NPs showed colocalization with SPARC, indicating that the SPARC-mediated pathway was involved in the glioma-targeting delivery." (PMID 29732051, 2018). "Sodium fluorescein, originally designed for ophthalmological use, has been adapted for enhancing contrast in intracranial tumors; however, its non-specific binding to serum albumin restricts its accuracy in glioma resection." (PMID 40426988, 2025). "The albumin nanoparticles modified with LMWP and containing two drugs, PTX/4-HPR, have proven to be effective in stopping tumor growth in subcutaneous and orthotopic glioma models." (PMID 37836018, 2023). "The effect of albumin as a DDS increases the blood residence time, and the effect of cRGD as a biological target increases tumor selectivity, which provides more intensive BNCT against high-grade gliomas compared with that with BPA." (PMID 36979069, 2023). "Several inflammatory indicators have been shown to predict the prognosis of patients with glioma, including platelet-to-lymphocyte ratio (PLR), lymphocyte-to-monocyte ratio (LMR), neutrophil-to-lymphocyte ratio (NLR), and the albumin to globular albumin ratio (AGR)." (PMID 36874094, 2023). "The authors have developed albumin-based NPs that have BBB-penetrating properties and can encapsulate different therapeutic drugs such as paclitaxel and fenretinide, exhibiting an improved treatment of glioma." (PMID 36109754, 2022). "Meanwhile, WBCs and neutrophil counts were significantly higher in patients with grade IV compared with other grades of glioma, while lymphocyte and monocyte counts and albumin levels were not significantly different." (PMID 36483052, 2022). "It is reasonable that the CNS-1 glioma cells that originate in the brain, an organ mostly deprived of albumin, do not express receptor/s for albumin, explaining the lack of uptake inhibition by BAF in these cells." (PMID 34683850, 2021). "In addition, albumin-based nanocarriers have been shown to engage cell-surface receptors, such as SPARC34 and gp6035, that are overexpressed on glioma cells and tumor vessel endothelium." (PMID 33173024, 2020). "Here, we presented an albumin-based biomimetic delivery system for codelivery of the disulfiram/copper complex (DSF/Cu) and the macrophage modulator regorafenib (Rego) via a so-called “two-birds-one-stone” strategy for targeting both glioma cells and TAM2." (PMID 29732051, 2018). "Increased levels of albumin (43.31 ± 4.02 vs. 42.65 ± 3.86, p = 0.029), AGR (1.92 ± 0.35 vs. 1.79 ± 0.35, p = 0.000), and PNI (52.81 ± 5.19 vs. 51.76 ± 5.32, p = 0.009) were found in men, in contrast to women with gliomas." (PMID 30154718, 2018). "In a rat RG2 glioma model, tesmilifene reduced transendothelial electrical resistance and inhibited key efflux transporters—P-gp/ABCB1, BCRP/ABCG2, and MRP1—resulting in a 2.7-fold increase in fluorescein accumulation and enhanced albumin permeability within tumor tissue." (PMID 40806198, 2025). "Peripheral blood tests, such as NLR, PLR, LMR, red cell volume distribution width (RDW), albumin/globulin ratio (AGR), albumin/gamma-glutamyl transferase ratio (AGgR) and fibrinogen, can refine patient stratification to therapy and predict survival outcomes in gliomas." (PMID 35250826, 2022). "The conjugation of bimodal HSA with undecahydro-closo-dodecaborate only slightly reduced human glioma cell line viability in the absence of irradiation (~30 μM of boronated albumin) but allowed for neutron capture and decreased tumor cell survival under epithermal neutron flux." (PMID 34770947, 2021).
glioma (continued). "In addition, biomarkers including the NLR, monocytes to lymphocytes ratio (MLR), platelets to lymphocytes (PLR), albumin (Alb), prognostic nutritional index (PNI), and systemic immune-inflammation index (SII) have been used frequently in glioma grading and prognosis in previous studies." (PMID 31805879, 2019).
coagulopathy (65 papers, 2015 to 2026). "In our study, although no direct causal relationship was identified between the two mechanisms, markedly low serum albumin levels appeared to be associated with an increased risk of bleeding and coagulopathy." (PMID 40648856, 2025). "We have previously reported a randomized clinical trial of 67 patients where point of care (POC) targeted coagulopathy management and intraoperative administration of 5% albumin led to significant reduction of blood loss and blood product consumption during the lung transplantation surgery." (PMID 36894877, 2023). "Therefore, despite an imbalance between population age and etiology of end-stage lung disease, intraoperative targeted coagulopathy management together with 5% albumin administration significantly reduced blood loss and blood product transfusion in the POC group." (PMID 36894877, 2023). "Again, higher WBC count (28.6%) and older age (23.8%) were the most frequently reported predictors of ED, followed by increased creatinine (9.5%), low albumin (9.5%), lower platelet count (4.8%), coagulopathy (4.8%), male gender (4.8%), and fever (4.8%)." (PMID 41440532, 2025). "These were, in decreasing order of frequency, higher WBC count, older age, increased creatinine, low albumin, lower platelet count, coagulopathy, and male gender." (PMID 41440532, 2025). "Aside from the continued inflammatory state (decreased lymphocyte counts and albumin), consumptive coagulopathy became progressively more severe with significantly decreased fibrinogen and further increases in APTT, PT, and D-dimers." (PMID 38140576, 2023). "The inflammatory state persisted (as shown by decreased lymphocyte counts and decreased albumin), and indications of coagulopathy intensified with a significant rise in APTT, PT, and D-dimers over baseline." (PMID 38140576, 2023). "A secondary analysis of the randomized clinical trial evaluating the effect of targeted coagulopathy management and intraoperative administration of 5% albumin on early lung allograft function after LuTx and 1-year survival was performed." (PMID 36894877, 2023). "First, a major limitation is that our study design contained two interventions in one study protocol (targeted coagulopathy management and 5% albumin in POC study group)." (PMID 36894877, 2023). "Two studies assessed the impact of endothelial cells and in vitro albumin-induced dilutional coagulopathy on thromboelastometry parameters using the NATEM assay." (PMID 35328210, 2022). "The degrees of CRP (inflammation), ISTH overt DIC score (coagulopathy) and nutrition status (albumin) on the first day were found to be important factors for PIICS development (standardized coefficient, 0.17, p < 0.001 and 0.09, p < 0.001, respectively)." (PMID 32824569, 2020). "Plasma is replaced with albumin 5% or fresh frozen plasma in patients with coagulopathy (prothrombin time >37 seconds; international normalized ratio >3; activated partial thromboplastin time >100 or fibrinogen level <100 mg/d)." (PMID 32513290, 2020). "In cases of massive administration of HES 130/0.4 and also of albumin, however, dilutional coagulopathy should be monitored and treated appropriately with fresh frozen plasma and platelet concentrate." (PMID 26768898, 2016). "The aim of our prospective unblinded observational cohort study was to compare the degree of dilutive coagulopathy after albumin and starch intra-operative fluid therapy." (PMID 26425342, 2015). "Furthermore, a portion of the colloid fluid should be replaced early with hyperoncotic albumin or fresh frozen plasma in cases of severe bleeding and coagulation disorders." (PMID 39792932, 2025). "Furthermore, coagulation disorders and low albumin concentrations were observed, requiring the administration of fresh frozen plasma and albumin supplementation." (PMID 39022510, 2024).